GAS6-AS1 (GAS6 antisense RNA 1)
Gene: Long non-coding RNA gene on chromosome 13 (113,815,630 to 113,845,744, forward strand). Ensembl gene ENSG00000233695.
Diseases named in the same sentence as GAS6-AS1 in open-access papers:
GAS6-AS1 is named in the same sentence as 4 diseases in open-access papers, as found by Europe PMC text mining. Sharing a sentence is not in itself a finding about the gene and the disease. The quoted sentences say what the papers report.
gastric cancer (1 paper, 2021). A primary or metastatic malignant neoplasm involving the stomach. "GAS6 antisense RNA 1 (GAS6-AS1) is a long non-coding RNA involved in hepatocellular carcinoma and gastric cancer." (PMID 34513660, 2021).
cancer (1 paper, 2020). A tumor composed of atypical neoplastic, often pleomorphic cells that invade other tissues.
GAS6-AS1 also shares sentences with these, for which no sentence is quoted: hepatocellular carcinoma (1 paper); myocardial infarction (1).